INS (insulin)
Diseases named in the same sentence as INS in open-access papers (continued):
Sharing a sentence is not in itself a finding about the gene and the disease.
Insulin resistance (continued). "Hepatic fat accumulation is frequently associated with hepatic insulin resistance, and the combined observation of hepatic steatosis, hyperinsulinemia, and glucose intolerance displayed by 3w SRD CBA mice suggested that they were insulin-resistant." (PMID 26085100, 2015). "Insulin resistance (IR) is a complicated condition in which three primary metabolic tissues that are sensitive to insulin, skeletal muscle, liver, and white adipose tissue (WAT) become less sensitive to insulin and its downstream metabolic actions under normal serum glucose concentrations." (PMID 26136779, 2015). "The insulin resistance might play a major role in the subjects who show catch-up growth while insulin secretion defect or impaired β-cell development plays a major role in the subjects who fail to undergo catch-up growth." (PMID 26345406, 2015). "Insulin measurement has a similar cost, but its use has been confined to the clinical diagnosis of selected endocrine conditions, like insulinomas, and to the measurement of insulin resistance, mostly for research purposes." (PMID 26241903, 2015). "Anti-TNF therapy may improve insulin resistance in RA patients by reversing defects in the phosphorylation/activation status of the insulin signaling pathway." (PMID 26110878, 2015). "Insulin resistance (IR) reduces reactivity of the target organ to blood insulin." (PMID 26146523, 2015). "Interestingly Let-7 overexpression in mice induces insulin resistance repressing the expression of several mediators of insulin signaling pathway." (PMID 26046362, 2015). "Besides the positive relationship between immune cells content in AT in the etiology of insulin resistance, this cluster indicates that, in obese women, the higher is the insulin level at fasting, the lower is the lipid metabolism signaling in AT." (PMID 25590576, 2015). "Hence, in this experimental paradigm, hepatic insulin resistance is manifested as a decrease in insulin-induced suppression of endogenous HGP." (PMID 26426068, 2015). "However, incessant exposure to elevated glucose and lipids is known to have detrimental effects on pancreatic β-cell insulin secretion and is correlated with onset of insulin resistance in the periphery." (PMID 26257839, 2015). "The seemingly inevitable progression to overt insulin resistance that characterizes MetS may in part be the consequence of the body’s attempt to cope with NAFLD by driving systemic insulin sensitivity and, thus, fatty acid breakdown." (PMID 26580662, 2015). "Of note, although mice fed the MCD diet develop peripheral insulin sensitivity, it is known that MCD diet associates with liver insulin resistance, which may mimic the liver effects of metabolic syndrome-phenotype associated with human NAFLD." (PMID 26017539, 2015). "Many studies have found that hepatic insulin resistance, i.e., the diminished ability of circulating insulin to suppress hepatic glucose production, is directly related to IHTG content, independent of age, sex, BMI, waist circumference, percent body fat, and visceral fat mass." (PMID 26102213, 2015). "In pathophysiology, insufficient insulin production in the setting of insulin resistance and inadequate insulin secretion in beta cell are two key features of T2DM, and lots of genetic variations are thought to contribute to the abnormal changes, and increase the risk of T2DM." (PMID 25888350, 2015). "In addition to its previously suggested role in treatment of insulin resistance, inhibition of PKCε has been proposed to act as a positive regulator of insulin availability." (PMID 26398746, 2015). "The inability of pancreatic islets to increase insulin secretion to a sufficient level to compensate for insulin resistance during pregnancy due to protein restriction could contribute the development of gestational diabetes." (PMID 25654754, 2015).
Insulin resistance (continued). "Moreover, in the case of insulin resistance and T2D, attenuation of lipolysis by insulin action is impaired leading to an increased rate of lipolysis and enhanced release of free fatty acids (FFA) in the circulation." (PMID 26180583, 2015). "Our findings showed that CLE effectively decreased the production of inflammatory mediators, such as IL-6, TNF-α, and FFA in db/db mice, which could be due to decreased HOMA-IR and insulin, constantly improving insulin resistance in target tissues." (PMID 25889508, 2015). "One of the mechanisms of insulin resistance is altered insulin signaling." (PMID 25821809, 2015). "Although OGIS and ratio of AUCinsulin over AUCglucose did not improve significantly, their combination (the so-called disposition index) increased significantly in the vitamin D group, suggesting indeed an amelioration of the compensatory mechanism of insulin resistance by insulin release." (PMID 26057782, 2015). "Here, we revisit the pathogenesis of T2DM in light of β cell dysfunction versus insulin resistance in East Asians and discuss ethnic differences in the contributions of insulin secretion and insulin resistance, together with incretin secretin and action, to glucose intolerance." (PMID 25944304, 2015). "In our previous work, we have shown that the major differences in insulin resistance begin to appear when the mice are approximately 15 months old, which is most likely due to a decrease of insulin sensitivity during aging in N mice and better maintenance in long-living mutants." (PMID 25935838, 2015). "In addition, increased insulin secretion is in part related to pancreatic islet hyperplasia with progression of insulin-resistance by HFD supply." (PMID 26540072, 2015). "Moreover, GSK3β is a major factor in insulin resistance via its role in the regulation of the insulin signaling pathway." (PMID 26296196, 2015). "There were no changes in other anthropometric (BMI, WC, SBP, or DBP) or biochemical (fasting blood glucose [FBG], 2-hour post-load blood glucose [2h-PG], fasting insulin [F-insulin], 2-hour post-load insulin [P-insulin], or insulin resistance [HOMA-IR], TC) indices." (PMID 26581652, 2015). "In addition, several studies on the pathogenesis of type 2 diabetes in Korean subjects reported that impaired insulin secretion was more prominent than insulin resistance, even in people with impaired glucose tolerance." (PMID 25810782, 2015). "Microvascular dysfunction may affect both peripheral vascular resistance and insulin-mediated glucose disposal, thereby contributing to hypertension and insulin resistance, respectively." (PMID 26549941, 2015). "Decreased insulin levels may be partially inferred from the reduction of insulin resistance with improved glycemic control." (PMID 26170902, 2015). "Furthermore, subjectively perceived insufficient, poor or short sleep is associated with several pre-diabetic features such as fasting hyperglycemia, elevated postprandial glucose and insulin levels or indices of whole-body insulin resistance." (PMID 25834642, 2015). "L-asp inhibits insulin synthesis by the pancreatic β cells, and L-asp-related hyperglycemia may occur readily in patients with insulin resistance." (PMID 26317422, 2015). "In a mixed cohort of offspring aged 25 who were growth restricted in utero, a significantly lower insulin-stimulated glucose uptake was observed compared to controls, as well as a higher plasma insulin concentration, suggesting the development of insulin resistance." (PMID 25685986, 2015). "The high fat postnatal group showed insulin resistance with elevated serum insulin in the males." (PMID 27099868, 2015). "Additionally, while fasting insulin correlates highly with other surrogate markers of insulin resistance (HOMA-IR, QUICKI), it clearly lacks the precision of more robust measures of insulin resistance, such as an insulin clamp." (PMID 24755002, 2014).
Insulin resistance (continued). "Moreover, PTEN specific deletion in muscle improves skeletal muscle insulin sensitivity and protects mice from insulin resistance." (PMID 24404172, 2014). "In accordance with the increase of BMI, insulin secretory function might be also increased to overcome the insulin resistance." (PMID 24586809, 2014). "In addition, MCP-1 inhibits insulin-dependent glucose uptake, and MCP-1-deficient mice lack insulin resistance." (PMID 24416415, 2014). "There is no doubt that exposure to excess insulin can cause global insulin resistance through a feedback loop that includes tyrosine-phosphorylated IRS1/2, PI3K, Akt, mTOR, S6K, and serine-phosphorylated IRS1/2." (PMID 24741073, 2014). "It not only induces insulin resistance but also impairs insulin secretion by pancreatic β-cells." (PMID 25019091, 2014). "Moreover, a study reported that TGFβ/Smad signaling is involved in regulating insulin gene and suggested its role in the development of insulin resistance." (PMID 24986741, 2014). "Indeed, it has been reported that ROS can induce insulin resistance, impair insulin synthesis, and impair beta cell insulin secretion." (PMID 25019091, 2014). "It has previously been reported that in late pregnancy, these obese dams have elevated serum insulin and leptin levels, but normal blood glucose, consistent with insulin resistance; however, the impact of maternal obesity on the placenta have not been examined." (PMID 24744907, 2014). "The extract can reduce serum insulin and improve insulin resistance in STZ-diabetic mice." (PMID 25177729, 2014). "In aged mice, the plasma insulin levels are elevated, and insulin resistance is accelerated." (PMID 24796965, 2014). "The overlapping observations on the insulin-induced platelet aggregation and cGMP contents in healthy individuals and patients with insulin resistance confirm that cGMP increase in platelets is the main mechanism of insulin-induced modulation of platelet function." (PMID 25601838, 2014). "High fat diets have been proposed as one of the factors which may lead to reduced insulin sensitivity, followed by insulin resistance and ultimately the development of type 2 diabetes." (PMID 24801635, 2014). "Our study shows that the associations between abnormal lipid and insulin levels with lung function appear already in young adults, and that insulin resistance is present in individuals without declared T2DM." (PMID 25524286, 2014). "Specifically, insulin resistance has been reported to reduce both nigrostriatal dopamine release and dopamine clearance in the brain, whereas insufficient insulin secretion results in reduced dopamine transporter and tyrosine hydroxylase mRNA in the substantia nigra." (PMID 24806840, 2014). "Feeding rats a high-fat diet (40 % energy from fat) did not affect serum lipid indices or glucose levels, but it induced insulin resistance as evidenced by the twofold increased serum insulin level and homeostasis model assessment-estimated insulin resistance (HOMA-IR) index." (PMID 24415067, 2014). "In conclusion, administration of compound 6, a triterpenoid saponin isolated from S. chinensis, significantly enhanced glucose uptake and activated HK and PK, thus ameliorating insulin resistance, in HepG2 cells with insulin resistance induced by high glucose and insulin." (PMID 24918297, 2014). "These kinases can then impair insulin signaling, finally lead to insulin resistance." (PMID 24651118, 2014). "As expected, overweight subjects had higher diastolic blood pressure (DBP), plasma insulin, insulin resistance index by homeostasis model assessment (HOMA-R), serum triglycerides, uric acid levels and lower high-density lipoprotein cholesterol (HDL-C) levels than the lean subjects." (PMID 24410779, 2014). "Impairment of GLUT4 expression, GLUT4 translocation and/or insulin signaling may influence insulin-stimulated glucose uptake, which lead to insulin resistance and hyperglycemia." (PMID 25375187, 2014).
Insulin resistance (continued). "The associations with fasting insulin and HOMA-IR suggest that this locus may play a role in insulin resistance in the pathogenesis of T2D." (PMID 24637646, 2014). "The absence of active β-cells is associated with a decrease in insulin level and an increase in peripheral insulin resistance, which results in excess glucose in the circulating blood." (PMID 24993916, 2014). "Taken together, these data including ours suggest that the higher response in insulin secretion to oral glucose loading might be due to the compensatory hypersecretion of insulin to maintain normal glucose homeostasis in the presence of insulin resistance." (PMID 25309595, 2014). "A reduction in HOMA-IR may indicate a reduction in insulin resistance and an increase in the Matsuda Index may imply an increase in insulin sensitivity." (PMID 24886409, 2014). "Insulin resistance in the peripheral tissues could facilitate insulin resistance in the brain by reducing brain insulin uptake and by increasing levels of Aβ." (PMID 25346723, 2014). "They include a decrease in insulin production and/or an increase in peripheral insulin resistance." (PMID 25298880, 2014). "Type II Diabetes shows insulin resistance that the body cells decrease insulin use." (PMID 25089247, 2014). "Thus, the reduction in exogenous basal insulin requirement is likely related to resolution of obesity-induced insulin resistance." (PMID 24668543, 2014). "Furthermore, GGDGT ameliorated insulin resistance by decreasing plasma levels of insulin, improving glucose tolerance, and restoring insulin signalling by recovery of IRS-1 expression in skeletal muscle tissues." (PMID 25416139, 2014). "Insulin resistance develops when insulin becomes less efficient in lowering blood sugar." (PMID 31667161, 2014). "Indeed, we found significant associations between the GPS on one hand and higher fasting plasma glucose, insulin and HbA1c levels and insulin resistance on the other." (PMID 24885863, 2014). "RS and GO not only lowered the levels of blood and plasma glucose, HbA1c, insulin and homeostasis model assessment of insulin resistance (HOMA-IR) with a simultaneous decrease in hepatic gluconeogenic enzymes activities and adiposity, but also improved preservation of the pancreatic β-cells." (PMID 25272231, 2014). "Interestingly, insulin resistance was improved as evaluated by the level of blood glucose and insulin." (PMID 25295245, 2014). "Therefore, our study fills an important gap in the literature by taking a discovery approach to characterizing and quantifying the human adipocyte secretome in both insulin sensitive and two different insulin resistance conditions." (PMID 24948903, 2014). "Of note, insulin concentrations at the end of the study were typically 2-fold greater than those at the start, while glucose levels remained unaltered, suggesting the development of insulin resistance." (PMID 24733551, 2014). "This allowed one to classify the systemic glucose intolerance in a patient as liver type (hepatic insulin resistance), muscle type (peripheral insulin resistance) or mixed type, i.e., both the liver and muscle are insulin resistant and responsible for the glucose intolerance." (PMID 25411646, 2014). "However, despite established roles of these different kinases in the insulin-resistant state contribution of oxidative stress in the exacerbation of insulin resistance via IRS-1 serine phosphorylation still needs to be established." (PMID 25143800, 2014). "Increased fasting insulin can promote both obesity and insulin resistance." (PMID 24505481, 2014). "These lipids interfere with insulin signaling and represent one of the key aspects that could contribute to insulin resistance in situations of high-fat feeding or lipid infusion." (PMID 24623376, 2014). "Interestingly, the IRS1-dependent insulin signaling in glomeruli seems to be attenuated in insulin resistance." (PMID 24982885, 2014).
Insulin resistance (continued). "T2DM rats fed with a HF-HS diet developed steatohepatitis and insulin resistance associated with elevated serum alanine aminotransferase (ALT), aspartate aminotransferase (AST), insulin levels and the non-alcoholic fatty liver disease (NAFLD) activity score (NAS)." (PMID 24404139, 2014). "These processes may be due to “insulin resistance,” i.e., insulin inhibits glucose production and promotes lipogenesis." (PMID 24978432, 2014). "This suggests that concerns about insulin initiation, or psychological insulin resistance, may exist independently of the belief that insulin may be beneficial." (PMID 24902877, 2014). "However, it has been shown that, in states of insulin resistance, insulin loses its ability to decrease glucose production, while maintaining the ability to stimulate lipogenesis." (PMID 25371775, 2014). "Galectin-3 levels correlated significantly with the glucose disposal rate (R = 0.71, P < 0.001), fasting insulin (R = −0.56, P < 0.01), homeostasis model assessment for insulin resistance (R = −0.52, P < 0.05), and the insulin sensitivity index (R = 0.62, P < 0.005)." (PMID 25302080, 2014). "As the multiple regression analysis shows, we consider that galectin-3 is associated with insulin resistance rather than insulin secretion in patients with type 2 diabetes." (PMID 25302080, 2014). "Most of the studies involving T2DM and insulin resistance utilize data from insulin-resistant or diabetic animal models, such as Zucker fatty (ZF) and Zucker diabetic fatty rats (ZDF), high-fat-fed mice, muscle IGF-1 receptor–lysine–arginine (MKR) mice, and lep/lep mice." (PMID 25029527, 2014). "While the anti-inflammatory role of IL-1Ra in the pancreas is well established in both mice and humans, the role of IL-1Ra in other insulin target tissues and the general role of systemic levels of IL-1Ra in the development of obesity and insulin resistance is still unclear." (PMID 25244011, 2014). "Although abdominal obesity is closely associated with insulin resistance (hyperinsulinaemia), hyperleptinaemia and glucose dysfunction, changes in seminal plasma concentrations of insulin, leptin and glucose in obese males has not previously been investigated." (PMID 24885899, 2014). "In addition, insulin resistance indicators, such as fasting insulin and HbA1c, abdominal adiposity (waist circumference) and serum albumin/globulin ratio were negatively associated circulating irisin level." (PMID 24709991, 2014). "Inflammatory cytokines secreted by adipose tissue have the ability to induce intercellular communication between insulin target cells, including those in adipose tissue, liver, and muscle, which contribute to systemic insulin resistance and an inflammatory state." (PMID 25053966, 2014). "BBE can reduce the insulin resistance and may regulate genes that can regulate the insulin secretion and the effects on STZ-diabetic mice." (PMID 25177729, 2014). "In experimental studies, uric acid levels were reported to induce insulin resistance by inhibiting the bioactivity of nitric oxide, which is essential for insulin-stimulated glucose uptake in skeletal muscle, and by promoting the secretion of inflammatory factors and adipocytokine." (PMID 25237894, 2014). "Insulin resistance, hyperinsulinaemia (either endogenous due to insulin resistance or exogenous due to administered insulin or insulin secretagogues) and elevated levels of IGF-1 reduce apoptosis and increase cell proliferation in target cells, leading to tumour development 36–79." (PMID 23668396, 2014). "It comprises reversible insulin secretion, defect partially, and some degree of insulin resistance." (PMID 24829925, 2014). "Impairments to metabolically critical or insulin sensitive tissues, especially adipose tissue, pancreas, liver, and skeletal muscle, may have profound effects on the development of insulin resistance and type 2 diabetes in offspring." (PMID 24967364, 2014).